CD4 (CD4 molecule)
Diseases named in the same sentence as CD4 in open-access papers (continued):
Sharing a sentence is not in itself a finding about the gene and the disease.
infection (continued). "However, HIV treatment with highly active antiretroviral therapy reduces infection rates and does not alter the bacteriologic distribution, unless the patient exhibits low CD4+T cell levels." (PMID 41031628, 2025). "Another animal model is the pigtailed macaque (Macaca nemestrina), which is highly susceptible to SIV infection, showing a drastic CD4 T cell depletion, the absence of SIV-specific antibodies, and developing encephalitis within a couple of weeks after infection." (PMID 39997464, 2025). "Furthermore, activated S-specific CD8+ but not CD4+ T cell frequency in the first days of infection correlates negatively with peak viral load and positively with viral clearance rate." (PMID 40472803, 2025). "The phenotype of this virus is a lack of infection of tissue-resident CD4 T cells." (PMID 40586616, 2025). "Indeed, CD4, CD8, and γδ T lymphocytes were present in the BALC as early as 6 days post-infection with swIAV, and swIAV-specific cells could be detected between D4 and D7 in PBMCs." (PMID 40484956, 2025). "An alternative explanation could be suppression by conventional regulatory CD4+ T cells but our data showed that regulatory T cells (Tregs) were activated in the first (not third) infection." (PMID 40214640, 2025). "Moreover, in the CD4 T-cell population, the expression levels of HLA DR kept rising until the sixth month post-infection, even though the percentage of activated cells did not change significantly." (PMID 41011738, 2025). "Moreover, even repeated high-dose intranasal infection of aP-primed baboons with B. pertussis did not trigger expansion of antigen-specific Th1-polarized IFN-γ-secreting CD4+ T cells in the aP-vaccinated animals." (PMID 40071951, 2025). "In addition, EcoHIV infection does not involve CD4, eliminating the boost to HIV spread via Nef-mediated CD4 downmodulation." (PMID 39532531, 2025). "A human T cell line equipped with the CD4-17b-VN circuit could effectively control VRC01 and N6-αCD3 secretion upon sensitization, suppress the infection of diverse subtypes of HIV-1 strains, and mediate specific bypass cytotoxic activity against infected and latency-reactivated cells." (PMID 39998238, 2025). "Additionally, we discuss the central role of interactions between CD4+ and CD8+ T cells, monocytes, NK cells, and B cells, which, although essential for immune control of the infection, may, when dysregulated, exacerbate pathogenesis." (PMID 41407556, 2025). "Treatment with 20 mg/kg probenecid, 20 mg/kg amoxicillin, the combination of 20 mg/kg probenecid and 20 mg/kg amoxicillin, and 100 mg/kg baicalin could restore the intensity of the CD3, CD4, and CD8 protein expression in the blood vessels of mice compared to the infection group (p < 0.05)." (PMID 40305201, 2025). "When stratifying the samples by the number of prior DENV infections (either 1 or 2+), we observed that the Th1/Th17 polarization differences in DENV-specific CD4+ T cells were no longer apparent, indicating that repeat infection is necessary to induce this Th1/Th17 subset." (PMID 39989460, 2025). "Additionally, swIAV infection also led to an increase of cells represented by cluster 10 which consisted of CD3+ T cells that were negative for CD4, CD8β and TCR-γδ, but CD2+CD8α+perforindim." (PMID 40484956, 2025). "Even though PLHIV who gain ≥200 cells/μL after 24 months are considered IR, it is important to highlight that if they do not achieve a CD4+ T-cell count of ≥500 cells/μL, they remain immunocompromised, with a reduced capacity to combat and control infection by other pathogens." (PMID 40260259, 2025). "CD4+ T follicular helper cells are critical for both physiological and MHV68-driven germinal center responses and were also increased at baseline and following MHV68 infection of SR-BI-/- mice, together with increased MHV68-specific CD8+ T cells in infected SR-BI-/- mice." (PMID 40444948, 2025).
infection (continued). "Further mechanistic studies indicated that the protective phenotype is primarily driven by CD4+ T cells: CD4+ T cells in miR-451−/− mice proliferated significantly more after infection, but their activation status was not significantly different from that of wild-type (WT) mice." (PMID 41451216, 2025). "The observed aberrations in memory and effector T cell subsets were most likely driven by the exhaustion of CD4+/CD8+ T cells characterized by increased PD-1−KLRG1+ frequencies, in response to high antigen loads in LysMcrePKCδflox/flox mice at earlier stages of infection." (PMID 40475622, 2025). "IFN-enriched CD4+ T and CD14+ monocyte subsets, previously characterized in dogs as tissue-patrolling or inflammatory responders, may constitute a surveillance network capable of rapid activation under stress or infection." (PMID 41488614, 2025). "In addition, the cytokine profile of the hypervirulent isolates in A/J mice had a profound IFNγ and IL-17 response, and lung resident CD4 T-cells isolated from A/J mice expressed significantly increased Th1 (CXCR3, Tbet) and Th17 (RORγT) markers compared with KN99α infection." (PMID 40029251, 2025). "CD4+ T cell activation showed no significant changes in Spi-C KO mice upon infection." (PMID 40746561, 2025). "As a surrogate of SARS-CoV-2 antigen after infection, we used peptides covering the immunodominant sequence domains of the SARS-CoV-2 Spike (Peptivator peptide pool [Miltenyi]) to stimulate CD14-depleted PBMCs and measure IFNγ+ and CD107a+ frequencies in both CD4+ and CD8+ primary T cells." (PMID 40503889, 2025). "Detected lower percentages of phenotypic CD4+ and CD8+ effector T memory cells at R2 could be suggestive of either their natural decline or exhaustion due to prolonged immune activation during the course of the infection." (PMID 39963186, 2025). "Furthermore, naïve T lymphocytes count (both CD4 + and CD8 + ) were higher in LIC-infected C3KO mice, whereas effector CD8 + T lymphocyte numbers declined during LIC infection - a phenomenon more pronounced in C3KO mice." (PMID 40236016, 2025). "CD4+ T helper cells recognise antigen through MHC class II and support the activation and persistence of CD8+ T cells, enhance antigen presentation by dendritic cells, and recruit other immune effector cells to the infection site or the tumour microenvironment." (PMID 40883510, 2025). "To determine whether Dnmt3a was necessary for de novo methylation at genes associated with alternative T helper lineages, we performed whole genome enzymatic methylation sequencing (WGEM-seq) on WT and Dnmt3a KO (CD4-Cre) Tfh and Th1 cells sorted from LCMV infected mice at 7 days post infection." (PMID 39677644, 2025). "In parallel to the induction of Th2 cells, elevated IFN-g production by CD4+ T cells was seen in all LN samples at day 6, but the percentage of T-bet+ Th1 cells remained unchanged, and the rate of IFN-g production leveled down in CD4+ T cells at day 14 post-infection." (PMID 40092986, 2025). "Previous mathematical models argued that CD8+ T cells could clear infections without CD4+ T cell help, provided that the viral replication rate remained low." (PMID 40756816, 2025). "Notably, levels of circulating human CXCL10 in persistently infected CD4 + cell-depleted mice were not statistically different than those of mice that resolved infection (12 dpi)." (PMID 40920821, 2025). "In an E. coli-induced model of infection, N-DC hybrids acquired both MHC class II and co-stimulatory markers, suggesting a role in host defense mechanisms, by efficiently eliminating bacteria via facilitation of enhanced presentation of bacterial antigens to CD4+ T cells." (PMID 40340446, 2025). "Flow cytometry analysis showed comparable frequencies and cell numbers of intraepithelial Ly6A+CCR9+CD4+ T cells in small intestines from Trim29fl/fl and Trim29IEC-KO adult mice before EMCV infection or from Trim29fl/fl and Trim29IEC-KO suckling mice before rotavirus infection." (PMID 39396665, 2025).
infection (continued). "Similarly to CD4 CM t cells, with the addition of ATG induction as a co-variate we found that the combination of lower level of EM TIGIT+ in the absence of ATG induction was the strongest predictor of freedom from infection (p ≤ 0.05)." (PMID 40475763, 2025). "Similarly, JRCSF achieved high infection rates of about 30% at 50 ng p24 in the inoculum, whereas the isolate was unable to replicate in macrophages without CD4+ T cell coculture." (PMID 40130873, 2025). "In addition, our findings are limited to individuals with self‐limited mpox infection and CD4 counts > 500 cells/μL, as no participants in our cohort required hospitalization or presented with severe complications." (PMID 41204857, 2025). "Focusing on CD4 T cells, we could identify a reduced median signal intensity for CD69 in HPV–positive (focal) compared to HPV–negative samples, which suggests lower activation of these cells during the infection (cluster X, FC of 0.90 and p-adj of 0.04)." (PMID 39836629, 2025). "These IL-10-producing effector CD8+T cells disappear in later stages as the infection is controlled, but IL-10 producing CD4+T cells (in SLOs) persist, indicating the involvement of different mechanisms for IL-10 production by these two different cell types (CD8+ and CD4+T cells)." (PMID 41009359, 2025). "During the onset of infection, the frequencies of circulating N-specific CD8+ and CD4+ T cells inversely correlate with upper airway viral loads and systemic inflammatory markers, suggesting that these N-specific T cell responses may be attributable to viral clearance prior to seroconversion." (PMID 40872762, 2025). "In addition, CD4 + IFNγ+ cells were not significantly altered 3, 5, and 14 days after primary infection in the C. auris and C. albicans infection." (PMID 40294061, 2025). "Many brain T cells in our dataset and the 21-day infection dataset were neither CD4 + nor CD8+, which could also be attributed to the protein expression of those genes being more abundant than RNA expression." (PMID 40386405, 2025). "Unlike CD8+ T cells, antigen-activated CD4+ T cells can differentiate into Th1, Th2, and Th17 effector cells, which are typically identified by secretion of signature cytokines, under different types of infections and exposures." (PMID 40391228, 2025). "Seshadri, Davis and colleagues show that individuals who do not develop an infection with Mycobacterium tuberculosis (Mtb), despite exposure to the bacteria and expansion of CD4+ T cell clones specific to Mtb antigens, show enrichment of TH17 cell and T regulatory functional programs." (PMID 38997431, 2024). "Interestingly, we observed differential Treg responses, wherein classical CD4+ Tregs were either not induced during infection or induced in both Ascaris and coinfected pigs, contrasting with a rise in CD8+FoxP3+ Treg seen only in Ascaris-infected pigs." (PMID 39140728, 2024). "CXCR6 is thus not essential for migration of CD4+ TIA cells to the site of infection." (PMID 38838013, 2024). "In the initial stages of infection by inducing the production of IFN-γ by T and NK lymphocytes which contribute to macrophage activation and phagocytosis, it supports the differentiation of lymphocytes into CD4+ and constitutes a functional bridge between innate and acquired immunity." (PMID 38399810, 2024). "Furthermore, recent work from our laboratory demonstrated that Chlamydia-specific CD4 T cells express low levels of the Th1 transcription factor T-bet and mice lacking T-bet expression resolve infection normally." (PMID 38166152, 2024). "During untreated chronic HIV infection, CD4+ T cells specific for human herpesviruses, including Epstein-Barr virus (EBV), cytomegalovirus (CMV), herpes simplex viruses types 1 and 2 (HSV1 and -2), as well as for HIV and other infections, become activated and serve as targets for HIV infection." (PMID 38833307, 2024).
infection (continued). "In those patients in whom TAT‐based vaccination was performed, increased memory CD4 and CD8 cells were observed alongside increased proviral DNA decay in animal models which may abrogate initial infection making this an attractive target for future vaccine design." (PMID 39319247, 2024). "The diversity of the gut microbiota of PLWH infected with SARS-CoV-2 co-infection, whose median CD4 + T cell count was 671 cells/μl before infection, was not significantly different from that of the HC or PLWH without SARS-CoV-2 infection, longer than one month after the acute phase." (PMID 38172680, 2024). "We examined the impact of infection with the wild-type strain of C. albicans on TIGIT expression in different organs and noted an increase in expression after the infection except for the percentages of CD4+ and CD8+ cells in circulating lymphocytes, which remained unchanged." (PMID 39109867, 2024). "The percentage of triple positive polyfunctional CD4+ T cells towards parental spike was slightly higher among patients with prior infection, whereas non-infected patients had slightly higher levels of TNFα+IL-2+ dual positive CD4+ T cells towards spike from BA.4/5." (PMID 38326340, 2024). "CD4+ T cells derived from EECs9,11 have exhibited susceptibility to infection with both R5-tropic and X4-tropic HIV, suggesting that passive resistance to infection is not explanatory for this phenotype." (PMID 39013460, 2024). "The HCMV-specific CD4+ T cells expressing CD45RA+, measured by a flow-cytometry-based assay using HCMV-infected DC (CFC-iDC) as stimulus, showed a more rapid increase during the first month after primary infection, whereas the increase in CD8+ T cells expressing CD45RA+ was less evident." (PMID 39336935, 2024). "Immunophenotyping of the Peyer’s patches and spleen did not reveal any significant changes in number or frequency of CD19+B cells, CD8+ T cells or CD4+ T cells upon infection with H. diminuta when compared to control, nor when comparing between the two genotypes." (PMID 39083533, 2024). "By comparing sublethal with lethal dose infection in vivo, we found that not the viral load but an increased number of CD4+/CD25+FoxP3+ Tregs may impair the immune response by suppressing virus specific CD8+ T cells and favors disease progression." (PMID 38979428, 2024). "The number and percentages of IFN-γ+ CD4+ T cells, IFN-γ+ γδ+ T cells, and particularly IL-17A+ CD4+ T cells and IL-17A+ γδ+ T cells in lung of EPS301-adjuvanted mice was markedly higher than that in other groups on day 112 post vaccination in response to infection." (PMID 39556597, 2024). "In the absence of infection, the splenic phagocyte population (CD4− CD8a− CD19− B220− CD11b+ splenocytes) of VAD mice contained a significantly (P < 0.05) larger proportion of neutrophils (CD4− CD8a− CD19− B220− CD11b+ Ly6G+ splenocytes) compared with control mice." (PMID 38374245, 2024). "In primary N. brasiliensis infection, the migration of CD4+ T cells is mandatory for host immunity, but the Th2 response to secondary infection is independent of both T cell migration and tertiary lymphoid structures in the lungs, observations similar to our findings here." (PMID 39273153, 2024). "Since this functional assay is reliant on the interaction of pMHC expressed by infected cells and TCR of primed CD4 and CD8 T cells, it was thus important to demonstrate permissiveness of cell lines to mycobacterial infection, as well as upregulation of cell surface MHC molecules post infection." (PMID 38956057, 2024). "Indeed, blocking of VLA-4 resulted in reduced numbers of IFN-γ+ CD4+ TIA cells and reverted bacterial titers to the level of control mice, confirming the relevance of the VLA-4-dependent recruitment to the site of infection for TIA-mediated protection." (PMID 38838013, 2024).
infection (continued). "M09 cells did not expand to higher levels on day 20 when administering αlL-10R from the time of initial infection, suggesting IL-10 does not regulate their late-rising phenotype, albeit IL-10 deficient mice show enhanced expansion of other MCMV-specific CD4 T cells." (PMID 38236791, 2024). "CD4+ T cells have been shown to elicit the most robust bacterial killing in the adaptive response in humans due to their production of the pro-inflammatory cytokine, IFN-γ, which activates macrophages in the adaptive phase to eliminate bacteria (most efficiently) at the later stages of infection." (PMID 39650648, 2024). "In addition, we evaluated whether there was a correlation between CD4 and GZMB at different infection status and latency profiles." (PMID 38273012, 2024). "A substantial proportion of the study population had CD4 counts at HIV diagnosis below 200 cells/μL (31.4% overall, 27.8% in MSM, 30.3% in PWID, 34.4% in MSW, and 47.9% in those with other or unknown modes of infection)." (PMID 38932178, 2024). "Interestingly, Foxp3 was mainly expressed in a subset of CD4+ T cells but not differently regulated in the lung during infection, suggesting a potential uncoupling of traditional regulatory T cell responses." (PMID 38535532, 2024). "Furthermore, we have shown that CD4 and CD8 T cell responses exhibit different patterns of activation after vaccination and highlight the evolving quality of CD8 T cell responses, characterised by increasing polyfunctionality after breakthrough infections." (PMID 39260039, 2024). "In addition, regulatory CD4 T-cells (Tregs) expressing ST2 are immunosuppressive and accumulate during the early phases of C. deneoformans 52D infection (up to 7 days post-infection), but are then replaced by more inflammatory Tregs as the infection progresses (past 14 days post-infection)." (PMID 38921412, 2024). "We provide a population genetic analysis to support the theory that selection is acting in favor of more and more resistant CD4 alleles in ape species harboring SIV endemically (gorillas and chimpanzees), but not in other ape species that lack SIV infections (bonobos and orangutans)." (PMID 38014262, 2024). "Notably, the fourth vaccine dose or a breakthrough infection did not significantly increase the frequency of S-wt-specific CD4+ or cTfh cells." (PMID 39640263, 2024). "The activation of CD4+ T cells did not change post-infection compared to pre-infection." (PMID 38812507, 2024). "CD4+ T-cell counts in peripheral blood did not significantly decline during infection." (PMID 39459950, 2024). "Thus, Ca Ski subclones produced an adequate amount of HIV-1 RT corresponding to protein levels in a natural infection (although in the epithelial cells, not in CD4+ T lymphocytes)." (PMID 38399969, 2024). "In contrast, CD4+ T cells are not required for viral clearance at later stages of infection." (PMID 39392861, 2024). "The role of CD4+ T cell help in the induction of primary effector CD8+ T cells during acute infection is less clear and might differ between distinct viruses, viral tissue tropism and kinetics of the infection." (PMID 39392861, 2024). "This difference was not explained by infection duration or CD4+ counts." (PMID 39460342, 2024). "As the most striking finding, dialysis convalescent patients mounted significantly higher levels of spike-specific CD4+ T cells than convalescent controls or infection-naive individuals, which was not confounded by the number of prior immunization events or differences in age." (PMID 38326340, 2024). "In addition, lack of CD4+ T cell help during primary infection results in memory CD8+ T cells which lack the capacity to respond during re-infection." (PMID 38197178, 2024). "Interestingly, HIV-1 has been seen to bind to CD4-negative cells for cell–cell transfer into T cells for productive infection (defined as infection that results in creation of infectious progeny)." (PMID 39205255, 2024).